HADHA (hydroxyacyl-CoA dehydrogenase trifunctional multienzyme complex subunit alpha)
Diseases named in the same sentence as HADHA in open-access papers (continued):
Sharing a sentence is not in itself a finding about the gene and the disease.
glioma (4 papers, 2017 to 2025). A benign or malignant brain and spinal cord tumor that arises from glial cells (astrocytes, oligodendrocytes, ependymal cells). "We also validated HADHA protein expression levels in normal brain astrocytes and glioma cells, finding that HADHA was generally highly expressed in glioma cell lines." (PMID 40750765, 2025). "Results showed higher HADHA protein levels in GBM compared to LGG and normal brain tissues, with HADHA localized to the cytoplasm, matching our previous findings in glioma cells." (PMID 40750765, 2025). "To investigate the role of HADHA in glioma, we knocked down HADHA in the high-expressing cell lines LN229 and U251, generating stable shRNA-expressing cell populations (shControl, shHADHA#1, and shHADHA#2)." (PMID 40750765, 2025). "HADHA, central to mitochondrial fatty acid beta-oxidation, plays a significant role in glioma through its impact on energy metabolism, cell proliferation, oxidative stress, immune response, and therapeutic targeting." (PMID 38566075, 2024). "Compared to the control group, the gliomas with HADHA knockdown in both cell lines showed significantly reduced volume and weight." (PMID 38566075, 2024). "Knockdown of HADHA inhibited glioma cell proliferation and diminished their migration and invasion capacities and influenced the tumor growth in vivo." (PMID 38566075, 2024). "HADHA significantly influences the development of gliomas, both in vivo and in vitro." (PMID 38566075, 2024). "Understanding HADHA's specific roles could lead to improved therapeutic approaches for glioma patients." (PMID 38566075, 2024). "Hence, HADHA significantly influences the development of gliomas, both in vivo and in vitro." (PMID 38566075, 2024). "To verify elevated HADHA protein levels in GBM, we conducted IHC staining for HADHA in an independent cohort, including 10 glioma and 5 normal brain tissue samples." (PMID 40750765, 2025). "The findings validate that HADHA and BMP2 exhibit significant expression levels in glioma tissues, potentially playing a role in the development and advancement of glioma." (PMID 38566075, 2024). "To deeply assess the effect of HADHA on gliomas in vivo, we chose two cell lines, LN229 and U251, and divided them into control groups and HADHA stable knockdown groups." (PMID 38566075, 2024).
Hepatic steatosis (4 papers, 2020 to 2024). Steatosis is a term used to denote lipid accumulation within hepatocytes. "Moreover, deficiency of the HADHA gene causes fetal growth retardation and neonatal hypoglycemia and those mice heterozygotes for the HADHA allele develop hepatic steatosis and insulin resistance." (PMID 38397903, 2024). "Knockdown of HADHA markedly aggravated hepatic steatosis, inflammation and oxidative stress in FFA-treated L02 cells, which was associated with the activation of MKK3/MAPK signalling pathways." (PMID 36376538, 2023). "Recent research findings show that acetylation of the mitochondrial β-oxidation enzyme HADHA modulates hepatic fatty acid oxidation activity, and HADHA may be a key regulator during the pathogenesis of fatty liver disease." (PMID 36376538, 2023). "In addition, HADHA overexpression in NAFLD mice inhibited the progression of hepatic steatosis." (PMID 36376538, 2023). "HADHA is a substrate widely regulated by SIRT3, and its 5 acetylation sites were significantly differentially acetylated among three hepatic steatosis groups (P < 0.05)." (PMID 37568219, 2023). "Furthermore, potential important proteins, such as HADHA, ACAT1, EHHADH, were predicted to be essential regulators during the pathogenesis of fatty liver disease." (PMID 32586350, 2020). "Furthermore, this study identified potential important proteins, such as HADHA, ACAT1, and EHHADH, which may be important regulatory factors being acetylation level modified in the development of fatty liver disease in dairy cows, potentially being therapeutic targets for NAFLD in human beings." (PMID 32586350, 2020). "Furthermore, this study identified potential important proteins, such as HADHA, ACAT1, and EHHADH, which may be important regulatory factors through modification of acetylation in the development of fatty liver disease in dairy cows and possible therapeutic targets for NAFLD in human beings." (PMID 32586350, 2020).
liver cancer (4 papers, 2020 to 2025). An epithelial or non-epithelial malignant neoplasm that arises from the liver. "In both liver cancer and clear cell renal cell carcinoma, HADHA overexpression leads to reduced lipid accumulation, supporting cancer cell proliferation and metastasis." (PMID 39327932, 2024). "HADHA, mainly located in cytoplasma, expressed prominently high in liver cancer tissues than in peritumors tissues (p < 0.001)." (PMID 32033570, 2020). "In liver cancer, the oncogene UBE20 ubiquitinates HADHA for degradation and promotes the reprogramming of lipid metabolism, thereby contributing to tumorigenesis and progression." (PMID 39327932, 2024). "Specifically, miR-193b regulates ALDH3A2 and let-7b interacts with ALDH7A1 in obesity, however, in liver cancer, miR-193b regulates ALDH7A1 and let-7b targets HADHA, they regulate different genes (miR-193b /ALDH7A1, let-7b/HADHA) that participate in the same functional process." (PMID 33121472, 2020).
Obesity (4 papers, 2009 to 2025). Accumulation of substantial excess body fat. "The level of HADHA K728ac was also increased in cartilage in humans and mice with OA and further amplified by obesity and lipid stress, coincident with in vitro observations." (PMID 40425566, 2025). "Increases in the mRNA levels of ACADSB, BCAT2, HADHA and both the A and B subunits of BCKDH suggested that BCAA catabolism is upregulated in the AA of obese cardiac surgery patients and particularly pronounced in class III obesity." (PMID 32903728, 2020).
(VLCAD) deficiency (3 papers, 2018 to 2024). "Apart from 54 LCHAD deficiency patients, the “HADHA ratio” was calculated in 19 patients with very-long-chain acyl-CoA dehydrogenase (VLCAD) deficiency." (PMID 37754774, 2023).
heart failure (3 papers, 2020 to 2024). Inability of the heart to pump blood at an adequate rate to meet tissue metabolic requirements. "Our study demonstrated that HADHA mutation diminishes mitochondrial function and contributes potentially to the organ (heart) failure and sudden death." (PMID 34462673, 2021).
hypertrophic cardiomyopathy (3 papers, 2018 to 2022). A condition in which the myocardium is hypertrophied without an obvious cause. "Human genome-wide association studies (GWAS) have indicated that mutations in HADHA and HADHB are associated with familial hypertrophic cardiomyopathy, and mutations in CPT1, ACADM, and ACAA2 genes are associated with impaired mitochondrial fatty acid β-oxidation." (PMID 32804947, 2020).
ovarian carcinoma (3 papers, 2023 to 2024). A malignant neoplasm originating from the surface ovarian epithelium. "To investigate the consequences of loss of HADHA expression, we established ovarian cancer cell line (HO-8910 and SK-OV-3) with HADHA knockdown using short hairpin RNA (shRNA) that expressed HADHA." (PMID 37986001, 2023). "Loss-of-function experiments targeting HADHA demonstrated that its suppression in ovarian cancer cells hindered cell growth and migration, while promoting apoptosis." (PMID 37986001, 2023). "To elucidate the underlying mechanism by which HADHA regulates ovarian cancer, we identified CDK1 as a target of HADHA." (PMID 37986001, 2023). "To unravel the mechanisms underlying the impacts of HADHA on ovarian cancer development, we conducted an Identified Peptide Mass Spectrometry (IPMS) analysis to identify proteins that interact with HADHA." (PMID 37986001, 2023). "Through its regulation of CDK1, HADHA influences critical cellular processes in ovarian cancer, providing insights into its pathogenic mechanism." (PMID 37986001, 2023). "In this study, our objective was to investigate the functional roles and pathogenic mechanisms of HADHA in ovarian cancer." (PMID 37986001, 2023). "Additionally, we assessed the prognostic value of HADHA in ovarian cancer and investigated the underlying downstream mechanism of its action." (PMID 37986001, 2023). "Our study highlights the involvement of HADHA in ovarian cancer tumorigenesis and suggests its potential as a promising prognostic marker in ovarian cancer." (PMID 37986001, 2023). "In order to elucidate the roles of HADHA in ovarian cancer pathogenesis, our initial objective was to assess its protein expression in ovarian cancer specimens and compare it with healthy controls." (PMID 37986001, 2023). "This research provides valuable insights into the role of HADHA in ovarian cancer and its potential as a prognostic marker." (PMID 37986001, 2023). "Despite these findings in other cancer types, our knowledge of the specific roles and potential mechanisms of HADHA in ovarian cancer is currently limited." (PMID 37986001, 2023). "Then, we delved into the mechanisms through which HADHA influences the progression of ovarian cancer." (PMID 37986001, 2023). "In this study, we conducted an analysis of HADHA expression levels in ovarian cancer to elucidate its potential functions." (PMID 37986001, 2023). "Our findings establish HADHA as a significant tumor-promoting factor in the development of ovarian cancer." (PMID 37986001, 2023). "Lentiviral-mediated short hairpin RNA (shRNA) was employed to interfere with HADHA expression in ovarian cancer cells." (PMID 37986001, 2023). "In summary, our current work demonstrated that unequivocally establishes that HADHA plays a pivotal role in promoting tumorigenesis in ovarian cancer through its modulation of CDK1." (PMID 37986001, 2023). "Taken together, these findings demonstrated that HADHA functions as a tumor-promoting factor in ovarian cancer." (PMID 37986001, 2023). "Further research is needed to explore the involvement of HADHA in ovarian cancer and elucidate its precise mechanisms of action in this context." (PMID 37986001, 2023). "Immunohistochemical (IHC) staining of an ovarian cancer tissue microarray revealed that HADHA expression was elevated in 50.9% of tumor samples (N = 108)." (PMID 37986001, 2023). "Afterward, univariate Cox regression analysis was performed to evaluate the prognostic value of each tryptophan metabolism-related gene in the TCGA ovarian cancer cohort, with IDO1, ALDH3A2, HADHA, OGDHL associated with risk values, and CAT, WARS1 involved in protective factors." (PMID 38468343, 2024). "In this study, we observed significant overexpression of HADHA in ovarian cancer." (PMID 37986001, 2023). "Our data revealed significant HADHA overexpression in both ovarian cancer tissues and cell lines." (PMID 37986001, 2023).
ovarian carcinoma (continued). "Additionally, xenograft tumor models were developed to visualize the impacts of HADHA/CDK1 on ovarian cancer progression." (PMID 37986001, 2023). "Finally, a panel of rescue experiments were conducted to illustrate the roles of HADHA/CDK1 in ovarian cancer development." (PMID 37986001, 2023). "Consequently, we put forth the hypothesis that HADHA facilitates the progression of ovarian cancer by upregulating CDK1, both in vitro and in vivo." (PMID 37986001, 2023). "Besides, HADHA emerged as a prognostic indicator for ovarian cancer patients." (PMID 37986001, 2023). "However, it is essential to acknowledge certain limitations in the study: it requires further clinical validation for HADHA’s prognostic marker potential, needs deeper exploration of molecular mechanisms and signaling pathways involved in HADHA-mediated effects on ovarian cancer progression." (PMID 37986001, 2023). "To shed light on the precise regulatory mechanism by which HADHA and CDK1 are intertwined in mediating ovarian cancer, we probed into the UPS." (PMID 37986001, 2023).
type 2 diabetes (3 papers, 2016 to 2023). "Hydroxyacyl-CoA dehydrogenase trifunctional multienzyme complex subunit alpha (HADHA) was also listed among the top pathways, which was consistent with a recent study showing that HADHA is involved in the development of type II diabetes via TGF-β regulation." (PMID 30618784, 2018).
clear cell renal cell carcinoma (2 papers, 2024). "In clear cell renal cell carcinoma, HADHA overexpression inhibits tumor growth by increasing the expression of CYB5R3 or ACAT1." (PMID 38253797, 2024). "In contrast, HADHA overexpression retards tumor growth in clear cell renal cell carcinoma and is correlated with favorable patient survival." (PMID 39327932, 2024). "Similarly, HADHA overexpression disrupts lipid metabolism and decreases the number of cytoplasmic lipid droplets, impairing the energy supply in clear cell renal cell carcinoma." (PMID 39327932, 2024).
COVID-19 (2 papers, 2022 to 2023). A disease caused by infection with severe acute respiratory syndrome coronavirus 2. "Variants in the HADHA gene, described in this and previous studies, might play a significant role both as a protective and risk factor in the severe course of COVID-19." (PMID 35955824, 2022). "We hypothesise that the identified protective variant localised in the HADHA gene improves fatty acid metabolism which fosters a COVID-19 mild outcome." (PMID 35955824, 2022). "Interestingly, one study showed that mutations in the HADHA gene should be considered as a risk factor for a severe outcome of COVID-19." (PMID 35955824, 2022).
dyslipidemia (2 papers, 2011 to 2016). "PPARα agonists used to treat dyslipidemia have been shown to moderately induce the expression of ACADL and ECHS1 in rat liver, and in rat heart muscle PPARα agonists increase the expression of ECHS1 and reduce the expression of HADHA/B." (PMID 21339799, 2011).
hyperglycaemia (2 papers, 2022 to 2023). "Hepatic HADHA induction lowered fasting hyperglycemia and improved glucose and pyruvate tolerance with reduced hepatic lipid deposition in a BDH1-dependent manner." (PMID 35046401, 2022).
inflammatory bowel disease (2 papers, 2020 to 2024). A spectrum of small and large bowel inflammatory diseases of unknown etiology. "HADHA is involved in long-chain fatty acid-induced autophagy of intestinal epithelial cells and is therefore proposed as a new therapeutic target for inflammatory bowel disease (IBD)." (PMID 32824240, 2020). "Accordingly, HADHA is essential for regulating energy metabolism and maintaining metabolic homeostasis, and HADHA dysfunction is involved in the pathogenesis of multiple human diseases, including metabolic disorders, cardiovascular diseases, and inflammatory bowel disease [8‒10]." (PMID 39327932, 2024).
Insulin resistance (2 papers, 2024 to 2025). Increased resistance towards insulin, that is, diminished effectiveness of insulin in reducing blood glucose levels. "In T2D, impaired HADHA function can disrupt fatty acid metabolism, potentially contributing to insulin resistance and metabolic disturbances." (PMID 40370100, 2025).
lung carcinoma (2 papers, 2023 to 2024). "Specifically, HADHA expression is associated with the response to platinum-based chemotherapy and is upregulated in cisplatin-resistant lung cancer cells." (PMID 39327932, 2024). "However, the function of HADHA in the mitochondrial respiratory chain is essential for lung cancer growth, and the loss of HADHA impairs energy production." (PMID 39327932, 2024). "In lung cancer and lymphoma, HADHA acts as an oncogene by promoting tumor cell proliferation and decreasing susceptibility to chemotherapy reagents." (PMID 39327932, 2024). "The TFP is a promising target to restrain tumor growth in lung carcinomas by targeting the activity of the HADHA enzyme." (PMID 37601653, 2023).
neuropathy (2 papers, 2022 to 2025). A disorder affecting the nervous system that manifests with pain, tingling, numbness, and/or muscle weakness. "This case also highlights the need for HADHA and HADHB to be included in neuropathy gene panels as MTPD may present as CMT." (PMID 40790338, 2025).
Non-alcoholic steatohepatitis (2 papers, 2022 to 2024). "Non-alcoholic steatohepatitis in rats fed with a high-fat diet resulted in the downregulation of HADHA protein expression in liver cells." (PMID 38397903, 2024). "Li analyzed the hepatic mitochondrial proteome of non-alcoholic steatohepatitis in rats fed an HF diet and found that the diet resulted in downregulation of HADHA protein expression in liver cells." (PMID 35327303, 2022).
Sepsis (2 papers, 2023 to 2025). Sepsis is defined as life-threatening organ dysfunction caused by a dysregulated host response to infection. "Furthermore, HADHA lactylation promotes sepsis-induced cardiac dysfunction, highlighting its potential as a novel therapeutic strategy for sepsis-associated myocardial depression." (PMID 40849305, 2025). "It was found that although HADHA protein levels were unchanged, sepsis significantly reduced HADHA acetylation levels compared with controls, which was reversed by ALDH2." (PMID 36992838, 2023). "This study provided a novel mechanism of myocardial pyroptosis through mitochondrial Histone deacetylase 3/HADHA- NOD-like receptor protein 3 inflammasome pathway and demonstrated a significant role of aldehyde dehydrogenase as a therapeutic target for myocardial pyroptosis in sepsis." (PMID 36992838, 2023).
steatosis (2 papers, 2023 to 2024). Increased lipid within the cytoplasm of cells. "HADHA Heterozygous mice fed with HFD showed enhanced steatosis associated with a reduction of SCs assembly and OXPHOS function." (PMID 39488787, 2024). "Finally, overexpression of HADHA alleviated steatosis and liver damage." (PMID 36376538, 2023). "In the HFD‐fed groups, livers obtained from WT mice (HADHA +/+, HFD+) showed microvesicular steatosis, while HADHA ±, HFD+ mice exhibited enhanced steatosis." (PMID 39488787, 2024). "Importantly, we demonstrated that overexpression of HADHA inhibited the expression of p-MAPK in NAFLD mice, reducing lipid accumulation and steatosis." (PMID 36376538, 2023).
acute monocytic leukemia (1 paper, 2021). Acute monoblastic leukemia (AML-M5), is one of the most common subtypes of acute myeloid leukemia (AML) that is either comprised of more than 80% of monoblasts (AML-M5a) or 30-80% monoblasts with (pro)monocytic differentiation (AML-M5b). "Furthermore, bone marrow adipocytes were found to promote acute monocytic leukemia (AMoL) survival via increased FAO, determined by detecting increasing levels of HADHA following AMoL co-culturing." (PMID 34842843, 2021).
amyloidosis (1 paper, 2020). A disorder characterized by the localized or diffuse accumulation of amyloid protein in various anatomic sites. "We also profiled CSF in the 5xFAD mouse model to validate amyloidosis-induced changes, and found consistent mitochondrial decreases (SOD2, PRDX3, ALDH6A1, ETFB, HADHA, and CYB5R3) in both human and mouse samples." (PMID 32711556, 2020).
autoimmune disease (1 paper, 2023). A disorder resulting from loss of function or tissue destruction of an organ or multiple organs, arising from humoral or cellular immune responses of the individual to their own tissue constituents. "Thus, the positive correlation between ZNF335 expression and human eTregs suggests a potential role of ZNF335 in human eTreg differentiation, and the reduction in ZNF335, HADHA, and MitoTracker expression in human Tregs may be associated with the pathogenesis of autoimmune diseases." (PMID 37843279, 2023).
central obesity (1 paper, 2011). "For HADHA/B, the minor G-allele associated with a decrease in risk of developing central obesity (ORadd = 0.93(0.87–0.99), Padd = 0.03)." (PMID 21339799, 2011).
colon cancer (1 paper, 2022). "We explored that circRNA HADHA (circHADHA) was upregulated in plasma from polyp patients, whereas it was downregulated in plasma from colon cancer patients." (PMID 36313671, 2022).